CD47 (CD47 molecule)
Diseases named in the same sentence as CD47 in open-access papers (continued):
Sharing a sentence is not in itself a finding about the gene and the disease.
tumor (continued). "This study hypothesized that blocking the “don’t eat me” anti-macrophage phagocytic signaling with anti-CD47 Ab and activating the “eat me” macrophage phagocytic signaling with anti-CTLA4 Ab could enhance anti-tumor efficacy." (PMID 38398223, 2024). "The evaluation of the anti-tumor effects of SIRPα-VEGFR1, a bispecific fusion protein that concurrently inhibits CD47 and VEGF, demonstrated significant tumor regression in the Hu-PDX1 model, comparable to the observed effects in the SIRPα-Fc + VEGFR1-Fc combination group." (PMID 38532108, 2024). "Together, these data suggest that tumor cell-intrinsic IFN-I signaling is essential for antitumor CD8+ T cell response induction likely via DC activation and IL-1β production in the context of CD47-SIRPα blockade therapy." (PMID 38982116, 2024). "The hMnO2 core could relieve tumor hypoxia by decomposing H2O2 to produce O2, with the relief of hypoxia, the CSCs niche would be destroyed and the CD47 expression would be downregulated, thereby enhancing the immune response." (PMID 38699238, 2024). "Tumor cells often evade the innate immune system by expressing CD47, a ‘do not eat me’ signal that inhibits phagocytosis when it binds to SIRPα on macrophages, thereby promoting tumor invasion." (PMID 38543204, 2024). "Tumor cells express the “do not eat me” signal CD47 to interact with SIRPα on macrophages, which contributes to escape immune elimination." (PMID 39516356, 2024). "The tumor vaccine that contains anti-CD47 VHH could induce suppression of tumor progression and improve the long-term survival of tumor-bearing mice by remodeling the TME." (PMID 38254860, 2024). "Furthermore, the integration of CD47 blockade, MET inhibitors, and anti-CTLA-4 therapy engages both the innate and adaptive immune systems, enhancing phagocytosis, reducing tumor growth, and strengthening immune responses." (PMID 39275127, 2024). "Here the authors engineer anti-EGFRvIII CAR T cells to secrete an optimized SIRPγ-derived CD47 blocker, showing that combining CAR T cell effector functions with enhanced macrophage-mediated tumor cell phagocytosis improves anti-tumor efficacy in preclinical models." (PMID 39521782, 2024). "The in vivo anti-tumor activity of NILK-2401 was investigated in a mouse xenograft model, using SNU-C1 as target cells, as well as in a syngeneic model using human SIRPα/human CD47 transgenic mice with MC38 transfected with human CEACAM5 and human CD47." (PMID 38720892, 2024). "Given that CD47 is a transmembrane glycoprotein in a tumor cell that delivers an inhibitory signal for macrophage phagocytosis, they subsequently examined microglia's capability to engulf IDH‐mutant cells with reduced CD47 levels." (PMID 38339779, 2024). "Conditioning of the MSCs with heat-inactivated iTCS reduced CD47 expression, suggesting that the effect was mediated by factors secreted by tumor cells and not due to nutrient deprivation." (PMID 39310770, 2024). "Moreover, in a subcutaneous transplantation tumor mouse model, the depletion of CD4+ T cells in mice using anti-CD4 Ab alongside anti-CD47 Ab therapy significantly diminished the effect of anti-CD47 Ab in promoting tumor vascular normalization." (PMID 38398223, 2024). "ATP inhibition significantly reduced the therapeutic efficacy of CD47-SIRPα ICB, and ATP administration largely rescued the failed efficacy of CD47-SIRPα ICB in IFNAR1 knockout tumors, suggesting that ATP is a major mediator downstream of tumor cell-intrinsic IFNAR signaling." (PMID 38982116, 2024). "CD47 is regarded as a ‘do not eat me’ signal overexpressed by tumor cells to avoid being phagocytosed by MΦs." (PMID 39596395, 2024). "Here, we find that tumor cell responsiveness to type I, but not type II interferons, is essential for CD47-SIRPα blockade immunotherapy in female mice." (PMID 38982116, 2024).
tumor (continued). "Among the 50 patients, 24 cases exhibited negative expression and 26 cases exhibited positive expression of CD47 in tumor tissues, while in adjacent non-cancerous tissues, 16 cases were negative and 4 cases were positive for CD47 expression." (PMID 39652550, 2024). "AK117, a novel CD47-targeting antibody, does not induce hemagglutination of RBCs while effectively blocking CD47 on tumor cells." (PMID 38429732, 2024). "We established a MC38 tumor model, which is characterized by an abundance of intra-tumoral macrophages, to assess the antitumor potential of SMC18, a small molecule inhibitor targeting both CD47/SIRPα and PD-1/PD-L1 interactions." (PMID 38462636, 2024). "Attempts to overcome this limitation have included the development of bispecific antibodies, such as TG-1801 and IMM0306, that target both CD47 and tumor cells, thereby aiming to restrict activity against non-tumor cells." (PMID 38786045, 2024). "The presence of a significant relationship between CD47 expression and metastasis in unclassified RCC cases may be promising for the use of anti-CD47 antibodies for this tumor, which has a poor prognosis." (PMID 39795582, 2024). "This study postulates that concurrently targeting CD47 and CTLA4 could intensify the anti-tumor effects by simultaneously blocking the “don’t eat me” signal while triggering the “eat me” signal." (PMID 38398223, 2024). "The direct effect of ROS on tumor cell proliferation or death unlikely contributes to tumor growth inhibition in the CD47-SIRPα blockade scenario, since without T cell-mediated immune response, the blockade cannot inhibit tumor growth at all." (PMID 38982116, 2024). "It was shown that CD47 is frequently overexpressed in CTCL cells and that the interaction with anti-CD47 antibodies induces phagocytosis of the malignant cells by macrophages but also modulates cells of the tumor microenvironment." (PMID 38473222, 2024). "Furthermore, our study substantiates that anti-CD47 Ab contributes to tumor vascular normalization by enhancing CD4+ T cell infiltration, highlighting the role of tumor vascular normalization in the anti-tumor effect of CD47 targeting." (PMID 38398223, 2024). "Antibody with the anti-CD47 Fab in the absence of the anti-CD38 Fab failed to elicit CDC of tumor cells." (PMID 38448430, 2024). "While previous studies show that complete CD47 ablation can favor suppression and even complete rejection of IgG-opsonized B16F10 tumors, inter-experimental variation is high, particularly regarding complete tumor rejection and clearance." (PMID 37066426, 2024). "The detail mechanism of anti-CD47 nanobody hu404 binds to CD47 on the tumor cells but not RBCs need further verification in the future." (PMID 38783333, 2024). "CBX3 and CD47 mRNA positively correlated in GBM datasets, while CBX3 negatively correlated with an immune score that represents immune cell infiltration in GBM tumor tissue." (PMID 39545414, 2024). "These CD38/CD47 BsAbs could selectively block the interaction between CD47 and SIRPα on CD38+/CD47+ tumor cells and induce tumor cell death in vitro and in vivo." (PMID 38983860, 2024). "This suggests that disrupting CD47-SIRP-α interaction may be pro-phagocytotic, thus potentially improving the therapeutic efficacy of anti-tumor mAbs." (PMID 39712032, 2024). "The anti-tumor response to CD47 blockade treatment in non-responding mice (Tac mice) was restored by contact transmission or oral transfer of commensal bacteria from responding Jax mice through mouse cohabitation." (PMID 38564002, 2024). "Preclinical and clinical trial data suggest that CD47 blockade is unlikely to be successful as a monotherapy because its efficacy requires the expression of pro-phagocytic signals on tumor cells." (PMID 37958404, 2023).
tumor (continued). "The major purpose for the design of 6MW3211 is to obtain therapeutic benefit by selectively blocking the interaction of CD47 and SIRPα on PD-L1 and CD47 double positive tumor cells, but not binding to CD47 expressing on RBCs and other normal cells." (PMID 36593962, 2023). "Consequently, targeting CD47-TSP-1 interactions holds therapeutic potential for controlling angiogenesis and inhibiting tumor growth in cancer treatment, based on these compelling findings." (PMID 38188674, 2023). "It has been demonstrated that blockade of the CD47/SIRPα signaling alone is insufficient to inhibit tumor growth in the absence of additional pro-phagocytic signals (e.g., Fc-FcγR-mediated effector function)." (PMID 36650558, 2023). "In the HCC xenograft mice model, Abrine suppressed the tumor growth, and promote the anti-HCC effect of anti-PD-1 antibody through increasing the infiltration of CD8+ T cells, decreasing Treg cells, and inhibiting PD-L1, and CD47 expression." (PMID 37334368, 2023). "Notably, studies in preclinical models have demonstrated that CD47-TSP-1 interactions play a regulatory role in angiogenesis and tumor growth." (PMID 38188674, 2023). "If not for all cancers, at least in CT-26 tumor model it seems that blocking both CD47 and PD-L1 axis needed for the best therapeutic response." (PMID 36774400, 2023). "Cohousing of tumor-bearing Jax mice with Tac mice restored the response of mice nonresponders (Tac mice) to CD47-based immunotherapy." (PMID 37868956, 2023). "On the other hand, The SIRPA/CD47 pathway is defined as the signal ‘do not eat me’, which recognizes CD47-expressing tumor cells as self-normal cells and results in the inhibition of phagocytosis." (PMID 37958467, 2023). "In SCLC, the blockade of ‘do not eat me’ signals conveyed by CD47 expression on tumor cells and its interaction with signal regulatory protein alpha (SIRPα) on macrophages increased phagocytic activity of macrophages and inhibited tumor growth." (PMID 36809334, 2023). "Systemic or intratumoral administration of the Bifidobacterium cocktail (B. bifidum, B. breve, B. lactis and B. longum) rescued the capability of tumor inhibition by CD47 blockade in mice nonresponders." (PMID 37868956, 2023). "The combination of B6H12 (CD47 antibody) and dinutuximab (GD2 antibody) increases the phagocytosis of neuroblastoma cells by microglia significantly, substantially enhances antitumor responses and extends tumor-free survival in a syngeneic model in NSG mice." (PMID 36882399, 2023). "Seven days after tumor inoculation (designated as day 0), the mice were randomized into six groups: G1, PBS; G2, anti-CD47 antibodies (Anti-CD47ab); G3, Fe-Bac-HlpA/EGFP-BLPs + AMF; G4, Fe-Bac-HlpA/CD47nb-BLPs; G5, Fe-Bac-HlpA/EGFP-BLPs + AMF + CD47nb; G6, Fe-Bac-HlpA/CD47nb-BLPs + AMF." (PMID 36959204, 2023). "Co-expression of PD-L1 and CD47 was found to be an independent prognostic indicator of poor survival in both LUAD and LUSC patients, suggesting they may cooperate to suppress tumor immunity." (PMID 37958404, 2023). "Although macrophage-based anti-tumor strategies so far have mainly focused on the inhibition of TAM recruitment, another novel immunotherapeutic strategy has recently shown success: the blockade of the “don’t eat me” pathway CD47/SIRPα." (PMID 37876933, 2023). "Conversely, RT-triggered overexpression of CD47 was observed in CT-2A tumor but not much in TAMCs and TILs." (PMID 36959214, 2023). "Administration of a Bifidobacterium cocktail (B. bifidum, B. longum, B. lactis, and B. breve) or STING agonist DMXAA synergized the anti-tumor efficacy of CD47 blockade in mice non-responders in a STING-dependent way." (PMID 37781354, 2023). "Basic histopathological markers such as tumor diameter, histologic grade, lymph node status, and molecular subtype (including information on ER, HER2 status, and Ki67) together with CD47 or combined CD47–CD68 were included in multivariate analyses of RFS (all cases)." (PMID 36598153, 2023).
tumor (continued). "In a study conducted by Arrieta, the expression of CD47 in the tumor tissue of patients with NSCLC was not statistically significant for PFS." (PMID 37569332, 2023). "In addition, combining ACOD1-depleted CAR-iMACs with immune checkpoint inhibitors (ICI), such as anti-CD47 or anti-PD1 antibodies, result in even stronger tumor suppressing effect." (PMID 37723178, 2023). "We assessed the effects of molecules and their complexes on cells’ viability, parameters of apoptosis induction, IL-10 secretion and expression of surface molecules, characterizing interactions of tumor cells with the immune microenvironment (PD-L1, TIM-3, CD47)." (PMID 36986829, 2023). "During the whole process of anti-CD47 antibody screening and optimization, binding to CD47 specifically expressed on tumor cells, but not RBCs was set as the first criteria." (PMID 36593962, 2023). "Enhanced M1 phagocytosis can be achieved by stimulating calreticulin or phosphatidylserine in tumor cells, or by blocking the CD47/SIRPα (“Do not eat me”) signaling axis." (PMID 37457707, 2023). "In addition, conditionally overexpressing KLF10 in MiaPaCa cells revealed that the levels of CD47, CD24, and CD44 expression on tumor cells were reduced by more than 50%." (PMID 37308977, 2023). "Upon co-binding of dual CAR-Ts to CD47 and TAG72 on the surface of tumor cells, CAR-Ts could start eradicating TAG72-positive malignant cells." (PMID 38146364, 2023). "There were no adverse effects of ICG-anti-CD47 on the histological structure of the tumor and normal uroepithelium." (PMID 36937442, 2023). "Furthermore, the specific binding of purified SIRPα-Fc and Siglec10-Fc to CD47 or CD24, respectively, enhanced macrophage‐mediated tumor cell phagocytosis in vitro." (PMID 38016957, 2023). "6MW3211 was confirmed the specific binding to CD47 on tumor cells but no cross with CD47 on RBCs at high dose condition (>20.0 mg/kg)." (PMID 36593962, 2023). "In all the samples we collected, high expression of CD47 was connected to CD163+ macrophage infiltration.In summary, the expression of CD47 may regulate TME through immune cell infiltration, thus regulating tumor progression." (PMID 37719086, 2023). "Signal regulatory protein α (SIRPα) on the surface of macrophages can help macrophages recognize “myself” and “non-me” cells, and the surface of tumor cells usually highly express the CD47 molecule." (PMID 36911723, 2023). "Using flow cytometry on dissociated human tumor and non-malignant lung tissues, they confirmed that CD47 expression was higher in tumors compared to normal cells, but also discovered that CD133+ LCSC had the highest expression levels overall." (PMID 37958404, 2023). "As already known, the subpopulation of cells that circulate in bloodstream, known as Circulating Tumor Cells, express CD47, the “do not eat me” signal that allows them to evade detection by the immune system." (PMID 38033871, 2023). "IMM2902 inhibits tumor cell growth by speeding up the endocytosis and degradation of HER2 and enhances the phagocytosis of macrophages against tumor cells by blocking the interaction between CD47 and SIRPα, which acts as a “don’t eat me” signal." (PMID 36831412, 2023). "Importantly, CD47‐SIRPα blockade with an anti‐CD47 antibody treatment significantly enhanced EGFR‐targeted cancer therapy and elicited much greater tumor growth inhibition than either treatment alone." (PMID 37541303, 2023). "By using anti-CD47 and anti-PD-L1, we were been able to suppress the negative checkpoint signal and orchestrated an immune response against tumor." (PMID 36774400, 2023). "Except for tumor cells, RBCs also expresses high levels of CD47 to deliver negative signals to protect RBCs from macrophage phagocytosis." (PMID 36593962, 2023). "CD47 is a “do not eat me signal” that serves as an innate immune checkpoint, allowing tumor cells to evade macrophage-mediated phagocytosis." (PMID 37468567, 2023).
tumor (continued). "CD47 antagonists can also enhance NK-mediated antibody-dependent cytotoxicity (ADCC) and complement-mediated cytotoxicity, promote cancer cell apoptosis, reduce cancer cell proliferation, and prevent tumor cell migration." (PMID 37371818, 2023). "To investigate whether the knockdown of CD47 affects inflammatory cytokines, we co-cultured liver cells extracted from the CDX model with tumor cells to detect cytokine expression in the culture supernatant." (PMID 36860925, 2023). "Furthermore, in esophageal squamous carcinoma, anti-CD47 treatment favors the expression of pro-inflammatory cytokines (IL-2 and IL-12, IFN-γ, TNF-β) and increases the tumor-infiltrating CD8+ T cells." (PMID 36829496, 2023). "H&E staining of sections from major organs also testified the role of secreted anti-CD47 scFv in delaying tumor cell infiltration and maintaining normal organ morphology and histology." (PMID 37781520, 2023). "The expression level of IFN-β was higher in tumor DCs derived from mice nonresponders treated with Bifidobacterium and CD47 blockade than those from mice only administrated with anti-CD47." (PMID 37868956, 2023). "Anti‐CD47‐PCM@NP, with the smart blockade of CD47‐SIRPα signaling in the target tumor cells, could induce efficient immunocapture and antitumor efficacy." (PMID 36683161, 2023). "On the contrary, the other 4 miRNAs that were downregulated in tumor tissues did not affect CD47 expression in the same assay." (PMID 36413402, 2023). "In the pharmacokinetics study, the tumor accumulation of the DiD‐labeled nanoparticle core in the PCM@NP/DiD and anti‐CD47‐PCM@NP/DiD groups was also efficiently prolonged compared to the NP/DiD group, which was of considerable significance for its further application and druggability." (PMID 36683161, 2023). "Interestingly, the tumor cells in two TNBC groups displayed different expression patterns of the critical immunotherapeutic targets, such as PD-1/L1, CTLA4, CD47, CDK4/6, PARP1/2 and DDR1/2." (PMID 36998014, 2023). "Furthermore, nanoformulations affected the expression of proteins responsible for interactions between the tumor and its immune microenvironment: surface markers (PD-L1, TIM3, CD47) and IL-10." (PMID 36986829, 2023). "Therefore, the synergic combination of anti-CD47 with anti-PD-1 and anti-CTLA-4 induces a delay in tumor growth and improves overall survival in mice." (PMID 36829496, 2023). "The CD47/SIRPα axis, which is engaged in macrophage-tumor immune escape, was not significantly affected by morphine." (PMID 37259426, 2023). "By extending the potential clinical application of CD47 blockade combined with CAR-T cells to a wider range of malignancies, these treatment modalities can reduce the survival of CSCs and thereby prevent tumor recurrence." (PMID 36810098, 2023). "Combining CD47 and PD-1/CTLA-4 blockade is another strategy that could enhance anti-tumor activity by relieving additional brakes on tumor immunity." (PMID 37958404, 2023). "Similar inhibition effects on tumour cells were observed in our fusion HAC NVs, which may also affect intracellular signalling of PD‐L1 and CD47." (PMID 37974395, 2023). "OS TME is known to be infiltrated with TAM, which masks them from phagocytic or killing effects of macrophages by expressing the CD47 marker on the surface, which result in the non-killing of these tumor cells." (PMID 36769180, 2023). "CD47-antibody-induced apoptosis occurs in tumor cells on hard substrates rather than soft gels, suggesting a requirement of substrate stiffness for CD47-modulated cancer development." (PMID 37241964, 2023). "For example, tumor stem cells can upregulate CD47 (“do not eat me”) and PD-L1 (“do not kill me”) signaling, limiting T-cell and macrophage infiltration inside the tumor in vivo." (PMID 36411870, 2022). "Notably, while targeting CD47 with monoclonal antibodies only removes the don’t-eat-me signal, reinforcement of IGS with CXCR4 ligands would provide eat-me signals on tumor cells as well." (PMID 35565443, 2022).